IL6 (interleukin 6)
Diseases named in the same sentence as IL6 in open-access papers (continued):
Sharing a sentence is not in itself a finding about the gene and the disease.
prostate tumor (continued). "Thus a more detailed classification for prostate tumor microenvironment and validation of downstream molecules may be helpful in order to characterize the role of IL-6 in regulating PCa progression." (PMID 35194188, 2022). "However, whether IL-6 alone can induce de novo prostate tumor initiation in an autologous state is unknown." (PMID 28077171, 2017). "Together, these data indicate that expression IL-6 not only intrinsically reprograms the prostate to express pro-tumorigenic genes but also primes a pro-inflammatory tissue microenvironment whereby the combinatory effect may contribute to prostate neoplasm." (PMID 28077171, 2017). "Thus, activation of the IL-6 pathway is an important mediator of the effects observed in ESE3KD cells and targeting IL-6 could be a useful strategy in the context of low ESE3/EHF expressing prostate tumors." (PMID 27732936, 2016). "IL-6 is also known to upregulate MCP1 expression, a chemotactic factor that recruits monocytes and is present at elevated levels in metastatic prostate tumor tissue." (PMID 40507238, 2025). "Intriguingly, prostate-specific IL-6 transgenic mice exhibit, in addition to autonomously induced IL-6/STAT3/IGF signaling axis-mediated prostate neoplasms, an amplification of PPAT inflammation." (PMID 35406450, 2022). "Immunohistochemistry analysis in mice prostate tumors showed that shBAT1 significantly increased TNF-α and IL-6 expression when compared to control and BAT1cDNA tumors." (PMID 36505884, 2022). "Determination of the expression and localization of IL-6 and IGF-1Ec in prostate tumors was examined by qRT-PCR and by IHC." (PMID 30134795, 2018). "Immunohistochemistry studies showed increased levels of STAT3 and IL-6, but low levels of programmed cell death protein 4 (PDCD4), in prostate tumor epithelial cells compared to adjacent perinormal prostate epithelial cells." (PMID 28467474, 2017). "To confirm our findings in human prostate tumors, we further examined the ERα, CD206, CCL5 and IL6 expressions in 14 human PCa tissue specimens by IHC staining." (PMID 26790618, 2016). "Several studies have shown that IL-6 and its downstream transcription factor STAT3 have been identified as core mediators involved in several steps of prostate tumor progression, including tumor initiation, tumor growth regulation and promotion of tumor metastasis." (PMID 36733309, 2023). "Besides, we identified IL-6 as a direct target of CHD1 and mediates the recruitment and activation of MDSC, which contributes to T cell suppression in the prostate tumors." (PMID 36776288, 2023). "Endothelial cells do not express IL-6R, so IL-6 regulates endothelial function only through transsignaling, being involved in multiple biologic processes in prostate tumors." (PMID 35464825, 2022). "IHC analysis showed that shBAT1 mice prostate tumors increased TNF-α, IL-6, and MMP-10 expression." (PMID 36505884, 2022). "We speculate that during the treatment of ADT, the function of AR was inhibited, IL-6 and STAT3 were activated for compensation, and the expression of IL-6 and STAT3 promoted the increased synthesis of FGG, thereby promoting the growth of the prostate tumor." (PMID 33995485, 2021). "It should be noted that IL-6 induced expression of COX2, which is important for CD16 induction on monocytes by activated platelets, is mediated by STAT3 in monocytic THP1 cells and prostatic tumor cells." (PMID 33488616, 2020). "Furthermore, other cytokines such as CCL2, RANKL, IL-6, CXCL8, and IL-1 are known to drive osteoclastogenesis and bone resorption: key events observed following prostate tumor metastasis to the bone." (PMID 32585812, 2020). "Decreased PR expression in prostate tumors may result in relatively high levels of SDF-1 and IL-6 secreted by stromal cells, consistent with the reports that SDF-1 and IL-6 levels are elevated in cancer tissue samples." (PMID 24664419, 2014).
disc degeneration (50 papers, 2012 to 2025). "It has also been demonstrated that increased serum IL-6 levels are associated with disc degeneration-related LBP." (PMID 37101594, 2023). "The C-allele (in IL6 promoter polymorphism rs1800796) was more frequent among the subjects with disc degeneration observed during MRI." (PMID 33494410, 2021). "Rigal and colleagues initially used a meta-analysis to validate the effects of genetic polymorphisms on disc degeneration and demonstrated that IL-6 rs1800797 polymorphism was identified as a positive gene locus of LDD." (PMID 32070384, 2020). "There are many IL6 polymorphisms that have been associated with disc degeneration, specifically rs1800797, rs1800796, rs1800795 and rs13006435." (PMID 29179499, 2017). "Another study regarding the genetic risk factors of disc degeneration among 12–14-year-old Danish children also showed that polymorphisms in genes that encode interleukin-6 are connected with disc degeneration, which may lead to disc herniation." (PMID 33494410, 2021). "It seems to indicate that IL-6 might act synergistically with other genetic factors contributing to the risk of disc degeneration." (PMID 32070384, 2020). "Furthermore, IL-6 levels are linked to the degree of disc degeneration and pain intensity." (PMID 37101594, 2023). "Inflammatory cytokines such as TNF-α, IL-1β, and IL-6 are known to promote disc degeneration by enhancing matrix degradation and inflammatory responses." (PMID 40467648, 2025). "Recent research highlights how immune cells such as macrophages, T cells, and B cells, along with cytokines like IL-1β, TNF-α, and IL-6, play dual roles in both exacerbating and potentially mitigating disc degeneration." (PMID 40688090, 2025). "Inflammation is a critical driver of disc degeneration, characterized by elevated levels of pro-inflammatory cytokines such as IL-1β, TNFα, and IL-6, which exacerbate ECM degradation through the upregulation of matrix-degrading enzymes (MMPs, aggrecanases)." (PMID 40305345, 2025). "According to research, patients with disc degeneration have higher serum IL-6 levels than healthy controls." (PMID 37101594, 2023). "In summary, plasma IL-6 and TNF-α concentrations were positively correlated with the degree of lumbar disc degeneration, and this association was most pronounced in the upper lumbar discs." (PMID 35096205, 2022). "Both ELISA and qRT-PCR analysis showed that the expression levels of inflammatory cytokines TNF-α, IL-1β, IL-6, and IL-17 were inhibited after overexpressing c-Jun in the disc degeneration rats." (PMID 34308759, 2021). "The alterations of several cytokines in peripheral blood of patients with degenerative disc diseases are consistent with those found in intervertebral discs, such as interleukin-6 and CCL5." (PMID 32487144, 2020). "We evaluated the protein levels of IL‐6, the mRNA of which was obviously elevated by IL‐17A treatment, and COX‐2, which is one of the major components of disc degeneration and which causes pain." (PMID 30207057, 2018). "In our study, we obtained a significant increase in the protein expression of IL-6 an anti-inflammatory cytokine, while there was a significant decrease of IL-10 that is a pro-inflammatory cytokine at the same time (15 days) of disc degeneration." (PMID 26997908, 2016). "Upregulated genes with known roles in disc degeneration included interleukin-6 (Il-6), matrix metallopeptidase 3 (Mmp3), and a disintegrin and metalloproteinase with thrombospondin motifs 5 (Adamts5)." (PMID 24171898, 2013). "This dual role makes IL-6’s function in disc degeneration complex and significant." (PMID 40688090, 2025). "The silencing of these gene would contribute to NFk-B activation by inducing the transcription of proinflammatory genes such as TNF-, IL-1, IL-6, and IL-8, as well as disc degeneration by upregulating the expression of matrix-degrading enzymes such as MMPs and ADAMTSs." (PMID 36768184, 2023).
disc degeneration (continued). "IL-6 is a widely investigated cytokine in the field of painful disc degeneration." (PMID 32714187, 2020). "Additionally, IL‐6 levels are found to be higher in patients with low back pain prompted by disc degeneration." (PMID 30900385, 2019). "Thus, this MS2‐GFP system is an effective tool for visualizing dynamic IL‐6 transcription regulation during disc degeneration therapy such as PEMF treatment." (PMID 28851112, 2018). "There is certain evidence in the literature that in a subgroup of patients, painful disc degeneration is characterized by increased levels of proinflammatory cytokines, e.g. interleukin 1β (IL-1β), interleukin 6 (IL-6), interleukin 8 (IL-8) and tumor necrosis factor α (TNF-α)." (PMID 22909087, 2012). "The sustained elevation of IL-6 and TNF-α levels in the IVDDG group at week five indicates that the healing process for disc degeneration is insufficient and ongoing." (PMID 40606908, 2025). "For instance, IL6 and TNF are well-documented mediators of inflammation and pain in disc degeneration." (PMID 40722613, 2025). "Recent studies have emphasized the role of inflammatory cytokines like IL-6 and TNF-α, which are not only markers of inflammation but also active contributors to disc degeneration." (PMID 40688090, 2025). "Rapamycin treatment decreased the gene expression of MMP-3, MMP-13, IL-1β, IL-6, TNF-α, and protein levels of P16 and P21 in bleomycin-treated AFSCs suggesting that potential of rapamycin for disc degenerative diseases." (PMID 40727644, 2025). "In rat LSI-induced disc degeneration models, AMD preserved type II collagen and proteoglycan content while reducing TNF-α and IL-6 secretion." (PMID 40868398, 2025). "IL-6, IL-1β and TNF-α show high levels in LDH, and their expression levels are affected by age and the degree of disc degeneration." (PMID 38268042, 2024). "Meanwhile, other researchers have identified that the levels of IL-1β, IL-6, IL-17, and TNF-α have a positive relationship with the degree of disc degeneration." (PMID 34308759, 2021). "In disc degeneration, AKT is phosphorylated, and activated in NPCs, which was realized by the several inflammatory responses, including IL-1β, IL-6, and TNFα." (PMID 32526705, 2020). "Multiple reports show that inflammatory cytokines such as IL‐1ß, IL‐6 and TNF‐α initiate the cascade that culminates in disc degeneration." (PMID 30900385, 2019). "During disc degeneration, it has been demonstrated that IVD cells secrete proinflammatory cytokines such as TNF‐α, IL‐1α, IL‐1β, IL‐6, and IL‐17." (PMID 31463438, 2018). "Biochemical analysis showed that IL-6 and TNF-α levels were within normal ranges in the groups treated with PRP and PRP + ropivacaine, whereas these levels remained elevated in the untreated disc degeneration groups, indicating ongoing effects of degeneration." (PMID 40606908, 2025). "The p38 MAPK can affect the expression of MMP1, MMP3, MMP13, IL-6, IL-8, COX-2, iNOS, and TGF-β, as well as control the expression of anabolic and anti-catabolic genes such as proteoglycans, collagen I protein and collagen II, leading to disc degeneration." (PMID 38313000, 2023). "Statistically significant increased expression of IL-1β, IL-6, IL-17, VEGF-A and CD31 was evident in the samples of the DDD group compared with the controls, that showed a strong correlation with the histological disc degeneration stage." (PMID 37626681, 2023). "Inflammation in the IVD can be characterized by an increased expression of pro-inflammatory molecules such as interleukin (IL)-6, IL-1β, and tumor necrosis factor alpha (TNF-α), and contributes to the development of degenerative disc disease (DDD) and low back pain (LBP)." (PMID 32714187, 2020). "Interleukin 6 and cathepsin B do not represent good biomarkers of degenerative intervertebral disc disease, since the level of such compounds is increased in the plasma of patients with fractures." (PMID 31482941, 2019).
disc degeneration (continued). "Other cytokines besides IL-1β (tumor necrosis factor (TNF)-α, IL-6, IL-8, prostaglandin E2 (PGE2), and nitric oxide (NO)) may also be involved in the complicated pathogenesis of disc degeneration, including upregulation of MMP genes." (PMID 27405858, 2016).
Impaired glucose tolerance (50 papers, 2007 to 2025). An abnormal resistance to glucose, i.e., a reduction in the ability to maintain glucose levels in the blood stream within normal limits following oral or intravenous administration of glucose. "Additionally, adipose tissue promotes the synthesis of interleukin-6 (IL-6), which is associated with impaired glucose tolerance." (PMID 39941214, 2025). "Increased IL-6 is associated with impaired glucose tolerance as well as IR in hepatocytes." (PMID 31887984, 2019). "Another study in patients with impaired glucose tolerance treated with simvastatin reported that addition of metformin reduced both IL-1β and IL-6 in LPS-treated peripheral blood monocytes." (PMID 32940892, 2021). "Circulating IL-6 levels are increased in insulin-resistant states, such as impaired glucose tolerance and T2DM." (PMID 33043822, 2020). "The levels of IL-6 were higher in the low dose of PN which may contribute to the insulin-resistant state and impaired glucose tolerance, while IL-6 levels were lower in the high dose of PN and metformin-treated mice." (PMID 37426418, 2023). "In addition, elevated serum IL-6 levels were found in individuals with impaired glucose tolerance and type 2 diabetes (T2DM)." (PMID 35557517, 2022). "Possible mechanisms proposed to be involved include inflammatory processes, as research has linked experimentally raised glucose levels with increased plasma cytokine levels (tumor necrosis factor-α, interleukin-6 and interleukin-10) in healthy individuals and those with impaired glucose tolerance." (PMID 24023897, 2013). "Herder and coworkers reported a significant increase of circulating MIF, CRP, and interleukin-6 (IL-6) in subjects with impaired glucose tolerance (IGT; n = 242) or T2D (n = 236) compared to normoglycemic controls (n = 244) (KORA S4 study; participants aged 55–74 years)." (PMID 20169173, 2010). "However, it is of note that these mice also demonstrated impaired glucose tolerance, associated with suppressed adipose leptin secretion and intestinal glucagon-like peptide-1 (GLP-1) release, suggesting that adipose IL-6 signaling is important in mediating glucose metabolism in vivo." (PMID 35557517, 2022). "Moreover, a recent intra-abdominal SAT implantation experiment showed that implantation of SAT could alleviate impaired glucose tolerance and lower serum IL-6 levels in mice fed a high-fat diet (HFD)." (PMID 34203452, 2021). "After 12 weeks of Eriomin supplementation with 200, 400, or 800 mg per day, there was a significant decrease in fasting glycemia, impaired glucose tolerance, HOMA‐IR, HbA1c, glucagon, C‐peptide, hsCRP, IL‐6, and TNF‐α." (PMID 31183921, 2019). "Elevated blood sugar levels lead to increased circulating levels of cytokines such as IL-6, TNF-α, and IL-18, which may contribute to impaired glucose tolerance even in healthy individuals through oxidative mechanisms." (PMID 41011276, 2025). "The obese phenotype at P21 was related to elevated serum concentration of leptin, but not of insulin, and an impaired glucose tolerance when compared to IL-6−/−SD." (PMID 35896539, 2022). "Positive association plasma MIF with impaired glucose tolerance and T2D independent of plasma CRP and IL-6." (PMID 26124760, 2015). "In female Turkish subjects, subjects with impaired glucose tolerance had higher fasting serum TNF-α levels than subjects with normal glucose tolerance (p < 0.01), and serum TNF-α and IL-6 concentrations were elevated during the glucose challenge (for each comparison, p < 0.01)." (PMID 21663637, 2011).
ovarian tumor (50 papers, 2009 to 2026). "In our system, the SASP program triggered by cisplatin therapy in Brca1-deficient ovarian tumors was limited to Ccl5, Cxcl10, and Il6 of the factors examined." (PMID 35082152, 2022). "Cyr61 and IL-6 levels of serum or ascites were determined by ELISA (Enzyme-Linked ImmunoSorbent Assay), while Cyr61 expressions of different ovarian tumor tissues were evaluated by IHC (Immunohistochemistry)." (PMID 31766991, 2019). "Ovarian tumor-associated macrophage derived proteins, including IL-6, IL-8, and VEGF-C, have been shown to promote cancer progression." (PMID 26751490, 2016). "It is probable that B7-H4 is at least in part regulated by JAK/STAT3 signaling downstream of IL-6 and IL-10 receptors in ovarian tumor-associated macrophages, but this has yet to be formally tested." (PMID 26343197, 2015). "CAFs associated with human breast and ovarian tumours express high levels of IL6, a pro-inflammatory signal and component of the CAF pro-inflammatory gene signature." (PMID 26512722, 2015). "Interleukin-6 (IL-6) inhibitors play a significant role as IL-6 is a crucial inflammatory cytokine that is upregulated by HIF-1α in ovarian tumors." (PMID 40136686, 2025). "The chemokine CCL2 is the major determinant of monocyte recruitment at tumor sites, whereas IL-6 is a growth factor for ovarian tumors." (PMID 40007535, 2025). "IL6’s impact on the immune landscape categorizes ovarian tumors as either “hot” or “cold”, with its levels driving immune suppression in “hot” tumors and stromal remodeling in “cold” tumors." (PMID 40427188, 2025). "We review how interleukin-6 influences the ovarian tumor microenvironment, determining its “hot” or “cold” characteristics." (PMID 40427188, 2025). "This research confirmed that chronic stress downregulated HDC expression in ovarian tumor models, upregulating the expressions of IL-6, p-STAT3, and S100A9." (PMID 39720595, 2024). "A novel mouse model that utilizes transgenic female mice bearing ovarian tumors to study cancer cachexia.Notable biomarkers of this model are, growth differentiating factor 15, interleukin-6, interleukin-1 beta, and tumor necrosis factor alpha." (PMID 37755304, 2023). "This consistency of the results obtained by both biosensors is also visible in the series of results for IL-6 concentration in the samples of blood plasma from patients undergoing ovarian tumor resection and endometrial cyst resection." (PMID 35735559, 2022). "Changes in IL-6 concentration in blood plasma before and after resection of ovarian tumor and endometrial cyst, as determined by the two developed biosensors, are given as an example of a real clinical application." (PMID 35735559, 2022). "The decrease in IL-6 expression is important since this cytokine is released by immunosuppressive TAMs and has a direct stimulatory effect on ovarian tumor cells." (PMID 35513776, 2022). "TAMs are recruited at ovarian tumor sites, and IL-6, IL-10, transforming growth factor (TGF)-β promote their differentiation in M2 macrophages, associated with tumor invasiveness, spread, and angiogenesis." (PMID 34503248, 2021). "In human breast and ovarian tumors, it has been shown that a high level of IL-6 produced by CAFs was a vital part to facilitate the stroma inflammation." (PMID 33771156, 2021). "According to a recent report, the IL-6-JAK/STAT3 interplay was found to correlate with increased ovarian tumor cell growth and resistance to chemotherapy." (PMID 34674640, 2021). "Based on these results, a tentative, paracrine-mediated, paraneoplastic pathway has been postulated in which IL-6 expressed and secreted by the ovarian tumor would increase TPO production by the liver." (PMID 32867390, 2020). "Several inflammatory molecules, including RANTES/CCL5, MCP-1/CCL2, and IL-6 were upregulated after transfection of murine ovarian tumor cells O/N with poly (I:C) (10 μg/ml), compared to the untreated cell supernatants." (PMID 30613350, 2018).